PER2 (period circadian regulator 2)
Diseases named in the same sentence as PER2 in open-access papers (continued):
Sharing a sentence is not in itself a finding about the gene and the disease.
gastric cancer (10 papers, 2015 to 2022). A primary or metastatic malignant neoplasm involving the stomach. "Disturbance of the circadian clock has been linked to cancer; specifically, deregulation of Per1 and Per2 have been connected to gastric cancer and suggested as prognostic markers." (PMID 25853007, 2015). "Per2 is an important core clock gene 6, 15, and existing studies have reported that Per2 expression is strikingly lower in a number of human cancers, such as gastric cancer and non-small cell lung cancer, and closely related to the development and progression of cancer 17-20." (PMID 32284762, 2020). "In contrast, PER2 is upregulated in gastric cancer (GC), as is CRY1 in the advanced stages of GC." (PMID 33114496, 2020). "Additionally, other research has not indicated associations between PER2 (rs934945) and gastric cancer." (PMID 31739444, 2019). "PER1 and PER2 genes are currently considered to be true tumor suppressor genes, as decreased expression of either (or both) has been reported in several types of human cancers and has been shown to be an independent predictor of poor prognosis in patients with gastric cancer." (PMID 31409384, 2019). "Researchers reported that PER2 and CRY1 were significantly upregulated in gastric cancer." (PMID 34721627, 2021).
lymphoma (10 papers, 2008 to 2025). A malignant (clonal) proliferation of B- lymphocytes or T- lymphocytes which involves the lymph nodes, bone marrow and/or extranodal sites. "Mice with PER2 gene mutations exhibited a tenfold higher risk of developing lymphoma following ionizing radiation compared to wild-type mice." (PMID 41142939, 2025). "For instance, mice with genetic alterations in Per2 are more susceptible to developing salivary gland hyperplasia, lymphoma, teratomas, liver, lung and ovarian cancers." (PMID 37215573, 2023). "Previous studies demonstrated that mutation or knock out of clock genes Per2, Cry1/Cry2 or Bmal1 also accelerated the development of lymphomas following whole body exposure to γ radiations." (PMID 27494874, 2016). "PER2 was found to be reduced in lymphoma and AML patient samples while overexpression of PER2 led to cell cycle arrest and loss of clonogenicity." (PMID 28674522, 2017). "Interestingly, PER2 is known to control cell growth of acute myeloid leukemia (AML) and lymphoma cell lines, and PER2 reduced expression was confirmed in AML patients." (PMID 33086498, 2020). "Its disruption might be involved in initiation and/or progression of AML, as significantly reduced expression of Per2 has been noted in lymphoma cell lines as well as in AML patient samples." (PMID 20353609, 2010).
osteosarcoma (10 papers, 2013 to 2025). A usually aggressive malignant bone-forming mesenchymal neoplasm, predominantly affecting adolescents and young adults. "To test the effects of DZnep on the mammalian clock, we exposed a human osteosarcoma cell line (U-2 OS) and PER2::LUC mouse embryonic fibroblasts (MEFs), expressing bioluminescent clock reporters, to DZnep concentrations." (PMID 32376902, 2020). "To test the feasibility of an in vitro CCD approach, we chose a commonly used circadian model, human U2 osteosarcoma (U2OS) cells expressing a Period2 (Per2) promoter-driven destabilized luciferase reporter (pPer2-dLuc)." (PMID 31039152, 2019). "Herein, the same core circadian clock genes that are rhythmically controlled by CRY1 in osteosarcoma cells are also bound by CRY1 in PCa (i.e., CRY1, CRY2, PER2, and PER3) showing concordance of binding across models regardless of circadian synchronization." (PMID 33452241, 2021). "Human osteosarcoma U2OS cells were engineered to express firefly luciferase reporters under control of BMAL1 promoter (U2OS-C26) and PER2 promoter (U2OS-D15), respectively." (PMID 34905700, 2021). "Moreover, in synchronized human U2OS osteosarcoma cells, which, in contrast to HeLa and HT1080 cells, possess a functional circadian oscillator, GAPVD1 was rhythmically associated with CSNK1D, and the strength of this interaction mirrored the binding of PER2 to CSNK1D." (PMID 33917494, 2021). "To test our hypothesis, we chose three different commonly used cellular circadian models, i.e., mouse embryonic fibroblasts (MEF) and hypothalamic neurons (N44) along with human osteosarcoma (U2OS) cell lines with two different circadian luciferase reporters (Bmal1 and Per2)." (PMID 35813500, 2022).
ovarian carcinoma (10 papers, 2020 to 2025). A malignant neoplasm originating from the surface ovarian epithelium. "A gene associated with the biological clock, Per2, can inhibit the growth and metastasis of ovarian cancer cells." (PMID 33083827, 2020). "In studies exploring the relationship between the PER2 gene and ovarian cancer development, PER2 was found to modulate autophagy by interfering with the PI3K/PKB signalling pathway." (PMID 41234362, 2025). "PER2 overexpression reduces autophagy levels, decelerates ovarian cancer growth, and inhibits tumour angiogenesis." (PMID 41234362, 2025). "Circadian rhythm gene PER2, which had a low expression in ovarian cancer cells, repressed the growth of ovarian cancer cell SKOV-3 and enhanced their sensitivity to cisplatin." (PMID 34330232, 2021). "Further, the expression of PER2 is reduced in ovarian cancer via inhibition of the PI3K (phosphatidylinositol 3-kinase) signaling pathway." (PMID 34966277, 2021). "Genes associated with the circadian rhythm (e.g., Period 1/2 (Per1, Per2)), inflammatory factors and tumor immune factors may be related to the occurrence and development of ovarian cancer." (PMID 33083827, 2020). "Similarly, Per2 has the same effect on PI3K/AKT downstream signaling in ovarian cancer." (PMID 35599595, 2022).
melanoma (9 papers, 2016 to 2024). A malignant, usually aggressive tumor composed of atypical, neoplastic melanocytes. "It was found that Per1, Per2, Clock, and Cry1 expression was reduced in the melanoma biopsies as compared to adjacent normal skin in the majority of melanoma patients." (PMID 27128901, 2016). "To determine whether time-modulated drug activity on the mouse melanoma was core clock dependent, we generated CRISPR-control (B16-CTL) and Bmal1 knockout (B16-Bmal1-KO) melanoma cells stably expressing Per2 promoter–driven luciferase (pPer2-dLuc)." (PMID 33579708, 2021). "Additionally, PER1 and PER2 in the TME induced chemoresistance and immunosuppression in a melanoma mouse model." (PMID 37524704, 2023). "By comparing biopsies from human melanoma to non-tumorous samples, they were able to show that the expression of Per1, Per2, Clock and Cry1 clock genes and corresponding protein levels in the nucleus were reduced by 30%–60% in melanoma versus normal skin." (PMID 27231897, 2016).
pancreatic cancer (9 papers, 2013 to 2024). "Overexpression of PER2 in pancreatic cancer cells inhibits cellular proliferation, increases apoptotic rates and had a synergistic effect with cisplatin." (PMID 31014368, 2019). "This is consistent with the report that overexpression of PER2 in human pancreatic cancer cells lines reduced cellular proliferation, inhibited cell-cycle progression, and induced apoptotic cell death and arrest." (PMID 24171174, 2013). "The core circadian clock gene BMAL1 acts as a potential anti-oncogene in pancreatic cancer; the loss of BMAL1 with PER2 accelerates lung tumorigenesis, and BMAL1 inhibits tumorigenesis and further increases the sensitivity of tongue squamous cell carcinoma to paclitaxel." (PMID 32231148, 2020). "The role of PER2 in mediating cancer chemoresistance was also demonstrated in pancreatic cancer." (PMID 33114496, 2020). "Recently, reduced PER2 expression has also been reported in pancreatic cancer and CRC." (PMID 24708606, 2014). "Moreover, the overexpression of PER1 and PER2 has been shown to impair tumor proliferation and induce apoptosis in lung, prostate, and pancreatic cancer, reinforcing the idea that the molecular clock machinery may be considered as a new therapeutic target." (PMID 29946530, 2018). "Additionally, the higher prevalence of the PER2 VNTR 4R/3R and 3R/3R genotypes in pancreatic cancer patients compared to healthy controls suggested that a greater proportion of the 3R allele in the PER2 VNTR may be a risk factor for pancreatic cancer." (PMID 38813085, 2024).
breast tumors (8 papers, 2010 to 2025). "In the same cohort, the T allele in the PER2 rs934945 SNP was generally associated with higher risk of development of breast tumors, as well as estrogen-/progesterone-positive breast tumors based on a DM." (PMID 37761843, 2023). "One study suggested that decreased expression of PER1 and PER2 in breast tumors was due to the methylation of the PER gene promoters." (PMID 33089179, 2019). "A significant decrease in PER1 and PER2 expression has been demonstrated in sporadic and familial primary breast tumours when compared to normal breast tissue." (PMID 30348208, 2018). "A previous study has shown that the rhythmic patterns of Per1 and Per2 mRNA expression disappeared in tumor cells of breast tumor bearing mice." (PMID 26337663, 2015). "Significantly decreased expression of Per1 has been observed between sporadic breast tumors and normal samples, as well as a further significant decrease between familial and sporadic breast tumors for both Per1 and Per2 suggesting a role for both in normal breast function." (PMID 20353609, 2010). "Both sporadic and familial breast tumors have decreased expression levels of PER1 and PER2 when compared to normal breast tissue." (PMID 33089179, 2019). "We found significantly decreased expression of CRY2, PER1, PER2 genes in the ER/PR negative breast tumors compared to the ER/PR positive tumors." (PMID 29958276, 2018).
Familial advanced sleep-phase syndrome (8 papers, 2010 to 2025). "The PER2 gene mutation, specifically phosphorylation at the S662 site, is associated with familial advanced sleep phase syndrome (FASPS)." (PMID 40243466, 2025). "Hamster tau mutants showing a short period behavioral rhythm have a missense mutation in the CKIε gene, and human familial advanced sleep phase syndrome (FASPS) with early sleep times is attributed to missense mutations of PER2 and CKIδ genes." (PMID 21179498, 2010). "A mutation found in the human Per2 gene causes familial advanced sleep phase syndrome (FASPS)." (PMID 21712997, 2011).
Hypertension (8 papers, 2009 to 2020). The presence of chronic increased pressure in the systemic arterial system. "Our main results herein are that Npas2 is linked to hypertension and that Per2 is associated with blood glucose levels." (PMID 19470168, 2009). "Now, we demonstrate herein the associations of Npas2 with hypertension and of Per2 with blood glucose levels." (PMID 19470168, 2009). "Npas2 was associated with hypertension and Per2 with blood glucose levels." (PMID 19470168, 2009). "Emerging evidence suggested that clock genes such as Baml, Ck1e, Cry1, Per1 and Per2 play an integral role in the development of hypertension and kidney disease." (PMID 28368364, 2017). "In contrast, gene expression profiling of Spontaneously Hypertensive (SHR) rats, a genetic model of hypertension, demonstrated decreased expression of Bmal1 and Npas2, while Per1, Per2, Per3, Cry1, Cry2, Bhlhe41 and Csnk1D were all upregulated compared to naïve WKY controls." (PMID 33127986, 2020). "Other studies have revealed associations between: polymorphisms in BMAL1 with hypertension and type 2 diabetes, hypertension and NPAS2 (CLOCK gene analogous), and glucose and PER2." (PMID 20712885, 2010).
insomnia (8 papers, 2010 to 2025). A sleep disorder characterized by difficulty in falling asleep and/or remaining asleep. "Zebrafish disrupted their own circadian rhythm after prolonged light treatment, causing insomnia and metabolic disorders in the body, which led to the low expression of cry1bb, cry1ba and per2 genes in zebrafish." (PMID 36765993, 2023). "More recent work has been in the Per genes, with a Chinese study finding a significant association between Per2 genotype and insomnia, as well as a G×E interaction with Per2, work stress, and insomnia." (PMID 27999387, 2016). "In particular, significant correlations were found between circadian properties of BMAL1 and PER2 with symptoms such as fatigue, insomnia, and nausea." (PMID 40382284, 2025). "Insomnia patients usually exhibit circadian rhythm disorders, and resveratrol can regulate the expression of biological clock genes BMAL1 and PER2 by activating SIRT1, thus adjusting the sleep–wake cycle and improving sleep quality." (PMID 40144750, 2025).
Insulin resistance (8 papers, 2016 to 2024). Increased resistance towards insulin, that is, diminished effectiveness of insulin in reducing blood glucose levels. "In support of this premise, an increase in PER2 was found to be associated with insulin resistance in the mouse liver and other conditions of increased oxidative stress such as fasting." (PMID 38250971, 2023). "Gene-based approach detected a significant association of CpG methylation pattern in PER2 gene with both blood glucose and insulin resistance There is a similar observation for CLOCK and BMAL genes." (PMID 32344535, 2020). "A gene-based approach detected a significant association of CpG methylation pattern in PER2 gene with both blood glucose and insulin resistance There is a similar observation for CLOCK and BMAL genes." (PMID 32344535, 2020). "Similarly, thiazolidinedione resolves the disruption of the expression of circadian clock-associated genes(Bmal1, Per2, Cry1), improving insulin resistance." (PMID 39165284, 2024). "At the level of q < 0.05, gene-based analysis detected significant associations of DNA methylation in four circadian genes (CLOCK, BMAL1, PER1, and PER2) with insulin resistance, fasting glucose, or HbA1c." (PMID 31031806, 2019). "The increasing trend of PER2 expression, seen in our study, may have contributed to insulin resistance, increased oxidative stress, and ectopic lipid accumulation evidenced earlier in the liver of this sheep model of prenatal BPA exposure." (PMID 38250971, 2023).
schizophrenia (8 papers, 2013 to 2025). A major psychotic disorder characterized by abnormalities in the perception or expression of reality. "Various studies reported disturbed circadian rhythms in schizophrenia patients or model systems in connection to PER2 and PER3 expression or gene polymorphisms." (PMID 34954808, 2022). "Circadian alterations in expression levels of CLOCK, CRY1, and PER2 mRNA were found in schizophrenia." (PMID 29534090, 2018). "Indeed, compared with healthy controls, schizophrenia patients presented disruptions in diurnal rhythms of the expression of Per1, Per3, and Npas2, accompanied by a delayed phase in the expression of Per2 and by a decreasing in Per3 and Npas2 expression." (PMID 28468274, 2017). "Another study suggested that Per3 but not Per2 abnormalities were associated with schizophrenia." (PMID 28468274, 2017). "On the other hand, skin fibroblasts isolated from patients with chronic schizophrenia lose rhythms in the expression of the clock genes CRY1 and PER2 when compared with healthy controls, and PER1/2/3 and NPAS2 mRNA levels were reported to be altered in white blood cells from schizophrenia patients." (PMID 32655359, 2020). "In individuals with first-episode schizophrenia, the mRNA expression of CLOCK, PER2, and CRY1 genes significantly decreases in the early stages, suggesting that the circadian rhythm disturbance may be part of the pathological process of schizophrenia rather than a result of long-term drug treatment." (PMID 40243466, 2025).
mood disorder (7 papers, 2010 to 2025). A cognitive disorder a disturbance in which the person's mood is hypothesized to be the main underlying feature. "Previous studies have demonstrated important associations of clock genes with sleep and mood disorders, as for example between PER2 variants and familial ASPS, between PER3 variants and diurnal preference and DSPS, and between CLOCK and mood disorders and human diurnal preference." (PMID 20174623, 2010).
acute myeloid leukemia (6 papers, 2010 to 2024). Acute myeloid leukemia (AML) is a group of neoplasms arising from precursor cells committed to the myeloid cell-line differentiation. "The results from a recent study suggest that Per2 is a downstream C/EBPα-target gene involved in acute myeloid leukemia (AML)." (PMID 20353609, 2010). "In acute myeloid leukemia (AML), PER2, PER3, and CRY levels are reduced due to reduced expression of CCAAT/enhancer-binding proteins (C/EBPs), while BMAL1, CLOCK, and PER1 levels increase." (PMID 34966277, 2021). "Similarly, MYC is overexpressed in acute myeloid leukemia (AML) and chronic lymphocytic leukemia (CLL) and is able to inhibit the expression of the circadian clock gene Period2 (Per2), which is highly expressed in neutrophils where it enhances antitumor proliferation." (PMID 36966168, 2023).
Cognitive impairment (6 papers, 2021 to 2025). Abnormal cognition is characterized by deficits in thinking, reasoning, or remembering. "Therefore, this study aimed to elucidate potential mechanisms implicated in MCI utilizing Per2 knockout (KO) mice, which have previously been shown to have cognitive deficits." (PMID 39002057, 2025). "Further research is needed to explore these interactions in more detail and to identify potential therapeutic targets for cognitive impairments related to Per2 dysregulation." (PMID 39002057, 2025). "This focus was motivated by previous findings demonstrating that Per2 KO leads to cognitive impairments through DRD1-PKA-CREB signaling changes, and METH treatment restores both cognitive function and gene expression levels." (PMID 39002057, 2025). "Pre-clinical studies suggest that NR enhances the performance of the clock genes BMAL1 and PER2, ameliorates chronic sleep deprivation-induced cognitive impairment, and may alleviate oxidative stress and mitochondrial impairment in microglia." (PMID 40573093, 2025). "Per2‐deficient (Per2−/−) mice showed an increased susceptibility to cognitive impairment according to the NOR and Y maze tests." (PMID 35713240, 2022). "Thus, morphine was used as a μ-opioid receptor agonist to determine whether cognitive impairment in Per2 KO mice could be restored after morphine treatment." (PMID 39002057, 2025). "However, the conclusion is that interactions between EPHB2, OPRM1, and PER2 lead to cognitive impairment, which is not sufficiently supported by the observed changes in expression levels." (PMID 39002057, 2025).